IL6 (interleukin 6)
Diseases named in the same sentence as IL6 in open-access papers (continued):
Sharing a sentence is not in itself a finding about the gene and the disease.
COVID-19 (continued). "Increased levels of serum ferritin, IL-6, and D-dimers have been associated with high mortality in patients with COVID-19." (PMID 36293381, 2022). "Our comprehensive profiling of serum cytokines highlights IL-6, above 50 other inflammatory mediators, as a likely driver of hypoferraemia in COVID-19; the strong association of IL-6 with serum iron is confirmed in our prospective cohort." (PMID 35935705, 2022). "In the case of COVID-19, IL-6 is one of the causes of lymphocytopenia via inhibiting lymphopoiesis through lymphocyte trafficking and the direct effect on progenitor cells." (PMID 36111104, 2022). "Here, we establish the electrophysiological basis underlying the arrhythmias seen in patients with COVID-19, using in-vivo and in-vitro guinea pigs treated with the combination of IL-6, AZM and HCQ." (PMID 35058480, 2022). "A recent study by Del Valle and colleagues showed that elevated levels of immune-biomarkers involved in the cytokine storm induced by COVID-19 at the time of hospitalization, like both IL-6 and TNF-α, were significantly associated with patients’ survival." (PMID 35453526, 2022). "High levels of IL-6 are linked to disease severity and poor prognosis in critically ill COVID-19 patients." (PMID 35409421, 2022). "Tocilizumab, a monoclonal anti-interleukin-6 (IL-6) antibody, has been identified as a possible therapeutic option for COVID-19 patients at risk of cytokine storms." (PMID 35261539, 2022). "Recently, the minor 299Gly (G) and 399Ile (T) alleles were also associated with a significant risk of severe COVID-19 (p < 0.001) and higher serum levels of interleukin 6 (IL-6)." (PMID 36231099, 2022). "As a critical mediator of the inflammatory response, IL-6 levels are obviously elevated among COVID-19 patients with complicated disease and are closely associated with adverse clinical outcomes." (PMID 36182930, 2022). "In fact, overproduction of IL-6 is a hallmark of severe COVID-19 with a critical role in exacerbating the excessive inflammatory response of the host." (PMID 36233516, 2022). "Using miRNA profiling to deconvolute CC abundance resulted in identifying sets of miRNAs that correlate in a severity-specific manner with CC already associated with COVID-19 severity such as IL6 and CXCL10." (PMID 34957382, 2022). "Levels of four cytokines (IL-6, IL-10, IL-18, IL-27) were consistently elevated in patients with COVID-19 independently of the variant." (PMID 36430621, 2022). "NF-κB initiates the first stage of inflammasome activation and induces the production of pro-inflammatory factors, including interleukin-6 (IL-6), a key cytokine associated with COVID-19 severity and mortality." (PMID 35811982, 2022). "Perhaps unexpectedly, several cytokines associated with severe COVID-19 and damaging cytokine overproduction (IL-6, IL-15, and IL-18) were reduced following coinfection at 5 d pvi." (PMID 35634338, 2022). "COVID-19 has been associated with the overactivation of the immune system; interleukin-6 (IL-6) seems to have a key role, which made its moderation to be proposed as a therapeutic blank." (PMID 36524015, 2022). "Increased pro-inflammatory cytokine levels of IL6 and TNFα can also cause lymphocytopenia in severe COVID-19 patients." (PMID 35784278, 2022). "In our study, CRP, IL-6, and IL-2R were independent risk factors for severe events in all enrolled COVID-19 patients in the univariate analysis, and CRP was an independent risk factor for severe events in the multivariate analysis." (PMID 36033814, 2022). "Tocilizumab, an interleukin-6 inhibitor, has been reported to minimize the risk of death in hospitalized severe-COVID-19 patients." (PMID 35566563, 2022). "The result of the meta-analysis showed that each increase in the IL-6 level of 1 pg/mL significantly increased the risk of mortality of COVID-19 patients (aHR = 1.0036; 95% CI 1.0010–1.0061; p = 0.006)." (PMID 35215138, 2022).
COVID-19 (continued). "High levels of IL-10 levels in early illness in patients with COVID-19 were shown to associate with poorer disease outcomes and was shown to be a predictor of severe disease along with IL-6." (PMID 35786403, 2022). "Several studies have consistently found an association between high plasma concentrations of IL-6 and IL-10 and increased COVID-19 severity." (PMID 36287506, 2022). "SARS-CoV-2 infection also appears to increase the production of IL-6 and IL-8, since higher levels of these cytokines are associated with more severe disease pathophysiology in COVID-19 patients." (PMID 35634307, 2022). "When we replicated these findings in a set of 195 patients with critical COVID-19 and 470 control subjects, we detected a significant association of IL-6 rs2069837 with COVID-19 (p = 8.89 × 10−3, OR = 0.67)." (PMID 35368020, 2022). "In patients with COVID-19 and obesity, high serum levels of IL-6 and TNF-α are negatively associated with T cells." (PMID 36615820, 2022). "The relationship between elevated PCT and COVID-19 severity can be explained by the associated systemic inflammation and the release of the proinflammatory cytokines such as IL-6, IL-1β, and TNF-α, with subsequent induction of PCT synthesis." (PMID 36295550, 2022). "Heightened IL-6 is associated with respiratory failure and the need for mechanical ventilation, marking it as an important cytokine in COVID-19 pathogenesis." (PMID 35572514, 2022). "Together, these findings indicate that PDM is associated with higher IL-6 serum levels and increased risk of severe COVID-19 (lung dysfunction, more frequent and prolonged hospitalization and ICU admission)." (PMID 35898449, 2022). "Of note, high levels of IL1B and IL6 have been linked to the worse prognosis in patients with COVID-19." (PMID 35705998, 2022). "Some studies have shown that COVID-19 severity is associated with increased levels of IL-6, which have been linked to changes in activity in the subgenual cingulate cortex and depression." (PMID 35053059, 2022). "Among pro-inflammatory cytokines, IL-6 is one of the most related to COVID-19, and is associated with a high risk of developing more severe diseases or mortality." (PMID 35055344, 2022). "In line, we observed increased systemic ACE2 concentrations in patients with severe COVID-19 that were associated with elevated Interleukin-6 (IL-6) levels." (PMID 35308535, 2022). "The cytokine IL-6 is a key proinflammatory mediator that is linked with disease severity and poor prognosis in COVID-19 patients." (PMID 35582921, 2022). "Accordingly, IL-6 inhibition has been associated with an increase in secondary infections in COVID-19 patients." (PMID 35386908, 2022). "COVID-19 is also associated with high levels of interleukin-6 (IL-6) and other pro-inflammatory cytokines." (PMID 36186126, 2022). "COVID-19 also causes serious inflammatory responses and many chemical drug therapies have been trialed such as corticosteroids, tocilizumab, IL-6 inhibitor, and intravenous immunoglobulin." (PMID 35203459, 2022). "The use of IL-6 blockers in COVID-19 hospitalized patients has been associated with a reduction in mortality compared to standard care." (PMID 35280907, 2022). "In this study, we investigate the use of the novel QDTI platform for measuring plasma IL-6 using an existing biobank of COVID-19 plasma samples and compare its diagnostic accuracy to a traditional Luminex assay." (PMID 35626318, 2022). "Though the glucocorticoid therapy can mount a response against the interleukin-6 mediated cytokine storm in COVID-19, its overuse has predisposed to the development of mucormycosis." (PMID 35719782, 2022). "One of the main cytokines linked to COVID-19 acute inflammation and the cytokine storm is the interleukin, IL-6." (PMID 36295089, 2022). "Increased plasma levels of IL6 are detected in approximately half of patients with COVID-19 and are associated with the disease severity." (PMID 35633962, 2022).
COVID-19 (continued). "A multi-center, retrospective study of 150 patients with severe COVID-19 showed a strong association between elevated ferritin and IL-6 levels and adverse clinical outcomes." (PMID 35079694, 2022). "Survival analyses revealed risk factors of patient age, baseline COVID-19 severity, and baseline IL-6 that affected survival time, especially in severely ill older patients." (PMID 35248063, 2022). "IL-6 is significantly elevated in severe COVID-19 patients and is associated with an increased risk of thrombosis, organ damage, and death." (PMID 35741174, 2022). "We observed a genome-wide significant association of IL-6 rs2069837 (p = 9.73 × 10−15, OR = 0.41) with critical COVID-19 in the discovery cohort, which included 437 patients and 2,551 normal controls." (PMID 35368020, 2022). "Among the cytokines, IL-6 is known as a causative factor in the pathogenesis and severity of COVID-19 due to various pleiotropic functions." (PMID 35619180, 2022). "The present study focused on dissecting the short-term discrete effects of systemic inflammatory activation, specifically IL-6 elevation, on QTc in patients with severe COVID-19 and exploring the underlying basic mechanisms." (PMID 35665254, 2022). "Higher levels of Casp1p20 and IL-18 which are inflammasome-derived products in the sera were found associated with COVID-19 severity and poor clinical outcome, including IL-6 and lactate dehydrogenase." (PMID 35582503, 2022). "Since severe COVID-19 is associated with a cytokine-release syndrome with increased interleukin-6 (IL-6), it seems reasonable to use monoclonal antibodies directed against key inflammatory cytokines as the treatment option." (PMID 35745658, 2022). "Many immune biomarkers have been associated with COVID-19 disease severity, including IL-6, IL-8, IL-10, IL-17A, IL-1RA, IFNγ, GM-CSF, HGF, CCL1, and CXCL13, however, specific roles in neuropathology have not been elucidated for all of them yet." (PMID 35665037, 2022). "The IL-6 polymorphism was proposed for use as an indicator of severity in COVID-19 patients in the Korean population." (PMID 35281455, 2022). "In conclusion, our study suggests that the screening of IL-6 signalling components at the hospital admission can identify patients at risk of severe COVID-19." (PMID 35634332, 2022). "A number of groups have described associations between elevated IL-6 and worse outcomes after COVID-19." (PMID 35308241, 2022). "Immune dysregulation in COVID-19 is reported to be mediated by IL-6 and in animal models low IL-6 concentrations were associated with less severe acute lung injury." (PMID 36422492, 2022). "IL-1β can potentiate IL-6 responses that are heavily implicated in excessive inflammation associated with COVID-19 pathogenesis." (PMID 36817759, 2022). "In conclusion, the present study shows that advanced age, the presence of comorbidities and elevated serum IL-6 levels are associated with the severity of COVID-19 and represent good markers to differentiate severe COVID-19 from mild clinical forms." (PMID 35846757, 2022). "In predisposed individuals, COVID-19 can induce Interleukin-6 (IL-6) dependent pathways related to cytokine storm and macrophage activation syndrome (MAS)." (PMID 35891442, 2022). "On the contrary, the minor allele rs2228145 was associated with higher plasma IL-6 levels in severe COVID-19 patients." (PMID 36204639, 2022). "This study suggested that the gut microbiota contributes to the induction of fever in COVID-19 patients by increasing the pathogenic bacteria in the GI tract, which stimulate the secretion of inflammatory cytokines, including IL-6." (PMID 35763685, 2022). "Patients with COVID-19 also depicted elevated levels of IL-6, whereas increased IL-6 is associated with cardiac dysfunction and can further increase the risk of cardiovascular incidents such as heart failure and myocardial infraction." (PMID 35711466, 2022).
COVID-19 (continued). "A raised level of serum IL-6 (cut-off—35 pg/mL) is associated with increased mortality and can be a useful prognostic marker in determining severity of COVID-19." (PMID 36366295, 2022). "IL­6 is a key factor of the cytokine storm of critically ill COVID-19 patients and increased level of IL-6 associates with higher death rate of the patients." (PMID 35139898, 2022). "Many studies reported increased levels of IL-6 during COVID-19 with the more pronounced elevation associated with severity and adverse clinical outcomes." (PMID 36287942, 2022). "Severe disease in COVID-19 is associated to increased neutrophil-to-lymphocyte ratio and high expression of neutrophil-related cytokines IL-8 and IL-6 in serum, and neutrophilia has been described as a predictor of poor outcome." (PMID 35720378, 2022). "Elevated IL-6 concentration was shown to be associated with detectable serum SARS-CoV-2 RNA in patients with COVID-19." (PMID 35185562, 2022). "In the initial study, we found that rs2069837 in the intronic of IL-6 was strongly associated with COVID-19 (p = 9.73 × 10−15)." (PMID 35368020, 2022). "For example, elevated levels of IL-6 has been associated with severe COVID-19 thereby highlighting IL-6 as a therapeutic target." (PMID 35757734, 2022). "These common genes were mainly involved in the inflammatory process caused by COVID-19-related cytokines, such as IL6 and IL1β." (PMID 35165525, 2022). "Chronic results after the infection of COVID-19, often linked with the cytokine storm of distinct inflammatory responses, trigger enhanced proinflammatory cytokines (IL-1 and IL-6)." (PMID 36092161, 2022). "The result of the meta-analysis showed that each increase in the IL-6 level of 1 pg/mL significantly increased the risk of mortality of COVID-19 patients (aOR = 1.0076; 95% CI 1.0004–1.0148; p = 0.04)." (PMID 35215138, 2022). "Increased serum levels of IL-6 and IL-8 have also been associated with disease severity in COVID-19 adult patients and enrichment of CCL20 has been observed in mechanically ventilated patients with COVID-19." (PMID 36279276, 2022). "In conclusion, compared with the adults with delta variant COVID-19, children tend to have lighter clinical manifestations, higher lymphocyte count, lower IL-6 level, less frequent liver injury, and milder clinical typing." (PMID 36076167, 2022). "Advanced age and the abnormal expression of some inflammatory cytokines including IFN-α, IL-8, and IL-6 have been proven to be closely associated with the prognosis of patients with COVID-19." (PMID 36466533, 2022). "Higher IL-17 levels in nasopharyngeal swabs and lung autopsies of COVID-19 patients were associated with higher levels of proinflammatory cytokines, including IL-1β, TNFα, IL-6, IL-8, and IL-23." (PMID 36136963, 2022). "First, ectopic fat exacerbates the inflammation caused by COVID-19 by the upregulation of proinflammatory cytokines like interleukin-6 (IL-6) and tumor necrosis factor-alpha (TNF-α), angiotensin II (ATII), and prothrombotics." (PMID 35721716, 2022). "Increased levels of WBC, neutrophils, CRP, ferritin, LDH, d-dimer, and IL-6, as well as decreased levels of lymphocytes, monocytes, and albumin have been associated with severe COVID-19 and worse outcomes." (PMID 35160073, 2022). "A total of 22 studies analyzed the association between TNF-α, IL-6, and vitamin D levels and the severity of COVID-19." (PMID 35215138, 2022). "For example, the levels of IL-6 produced by macrophages in cancer and COVID-19 are associated with the severity of the disease." (PMID 35480895, 2022). "IL-6 is one of the key mediators of the immune system and recently has been reported as a critical cytokine in COVID-19 associated CS." (PMID 35500008, 2022). "IL-6 is a key inflammatory mediator associated with COVID-19 severity and inflammation-related COVID." (PMID 36698809, 2022). "While an increased serum IL-6 has long been associated with severe sepsis in humans, it is now linked to severe COVID-19." (PMID 35308241, 2022).
COVID-19 (continued). "Hypertension (HTN) (p=0.008), CLD (p=0.02), TLC (p<0.001), NLR (p=0.004), AST (p=0.04), CRP (p=0.005), IL-6 (p=0.02) were associated with need for ICU care among hospitalized COVID-19 patients." (PMID 36060343, 2022). "Serum cytokine levels that are elevated in patients with COVID-19-associated cytokine storm include IL-1β, IL-6, TNF, IFN-γ and MIP-1." (PMID 33397398, 2021). "Our results showed that IL-6 (receptor) antagonists are effective in reducing mortality in COVID-19 patients, while the risk of side effects was higher." (PMID 34728658, 2021). "The model suggested TT3 (P-value 0.01), IL-6 (P-value <0.01), and Procalcitonin (P-value 0.03) as independent risk factors for COVID-19." (PMID 33784355, 2021). "Analysis within COVID-19 cases revealed 203 proteins associated with disease severity, the strongest of which was IL6." (PMID 33704068, 2021). "Infected macrophages were reported to have also increased expression of IL-6, a cytokine known to induce apoptosis in lymphocytes and potentially a cause of lymphopenia in COVID-19 patients." (PMID 34199761, 2021). "It is currently admitted that severe forms of COVID-19 are associated with a release of cytokines and chemokines such as IL-2, IL-6, IL-7, IL-10, tumor necrosis factor (TNF), and granulocyte colony-stimulating factor (GCSF)." (PMID 34552938, 2021). "Antibiotics like linezolid and vancomycin can augment cytokine production (TNF-α, IL-1β, IL-6, IL-10) by activating Toll-like receptors (TLRs), being associated with the possible pathophysiology of antibiotic-induced septic shock in COVID-19 patients." (PMID 34909910, 2021). "Genomic analysis revealed that critically ill patients with COVID-19 exhibit genetic variations in IL-6-mediated inflammatory pathway proteins, which cause life-threatening disease." (PMID 34159203, 2021). "Interleukin-6 (IL-6) and other cytokines are increased in patients with COVID-19, and IL-6 was also found to be a hallmark predictor for COVID-19 progression." (PMID 34483914, 2021). "It has also been reported that the main causes of inflammatory cytokine storm in COVID-19 patients are interleukin-6 (IL-6) and the NOD-like receptor protein 3 (NLRP3) inflammasome." (PMID 34831321, 2021). "For example, a recent study reported the significant role of IL-6 as an independent COVID-19 risk factor using multivariate logistic regression analyses." (PMID 34046036, 2021). "C-reactive protein, a protein whose expression is driven by IL-6, is a biomarker of severe infection that has been associated with the inflammation cytokine storm related to COVID-19." (PMID 33657157, 2021). "In our analysis we observed that several biomarkers, including GM-CSF, MCP-1, MIP1α, TNFα, IL-1RA, IL-6, IL-8, IL-15 and IL-10 were associated with fatal outcomes in COVID-19." (PMID 34539631, 2021). "IL-6 increases the risk for the development of COVID-19 severity and mortality by stimulating acute phase responses, specific immune reactions, and hematopoiesis." (PMID 34806090, 2021). "Following reports that IL-6 is a critical factor of the cytokine storm associated with COVID-19, monoclonal antibodies against IL-6 have been proposed as a therapeutic agent." (PMID 34603758, 2021). "It is also observed that aged persons are prone to develop B—lymphocytes (double-negative B cells) that are able to secrete pro-inflammatory mediators such as TNF-α, IL-6 and IL-8 and have been implicated in clinical manifestation of COVID-19." (PMID 35010301, 2021). "IL-6 release from skeletal muscles is linked to glycogen depletion in muscle, which is in contrast to what is observed in COVID-19 and related diseases, where IL-6 elevation is a result of injury and inflammation in infected cells/tissues." (PMID 34639569, 2021). "Specifically in COVID-19-associated systemic inflammation, severe disease is associated with increased levels of cytokines such as interleukin (IL)-6, tumor necrosis factor (TNF)-α, and IL-2R." (PMID 33074525, 2021).